ECM1 (extracellular matrix protein 1)
Diseases named in the same sentence as ECM1 in open-access papers (continued):
Sharing a sentence is not in itself a finding about the gene and the disease.
melanoma (2 papers, 2013 to 2021). A malignant, usually aggressive tumor composed of atypical, neoplastic melanocytes. "ECM1 knockdown reduces melanoma cell attachment and is consistent with findings that ECM1 overexpression has been associated with a poor prognosis." (PMID 24023917, 2013). "To summarize, our studies show that TFAP2C is an important player in the regulation of ECM1 expression in melanoma cells and that its effect is mediated by direct interaction with the ECM1 promoter." (PMID 24023917, 2013). "To the best of our knowledge, we are the first group to evaluate this and show that ECM1 is also over-expressed in selected melanoma cell lines, when compared to primary melanocytes." (PMID 24023917, 2013). "Our investigations show an as yet unrecognized role for TFAP2C in melanoma via its regulation of ECM1." (PMID 24023917, 2013). "In this study, we found that ECM1 is over-expressed in several melanoma cell lines, when compared to primary melanocytes, and furthermore, that ECM1 expression paralleled that of TFAP2C levels in multiple cell lines." (PMID 24023917, 2013). "We hypothesized that ECM1 is over-expressed in melanoma cell lines and furthermore, based on the discussion above, that ECM1 expression is regulated by TFAP2." (PMID 24023917, 2013). "However, knowledge regarding the expression of ECM1 in melanomas and the mechanisms of ECM1 regulation is limited." (PMID 24023917, 2013). "melanocytes and melanoma cell lines were screened for ECM1 expression." (PMID 24023917, 2013). "While TFAP2A has been extensively studied in melanoma, our investigations show an as yet unrecognized and understudied role for TFAP2C in this malignancy via its regulation of ECM1 expression." (PMID 24023917, 2013). "Since ECM1 levels appeared to have an inverse correlation with TFAP2A expression (in contrast to that observed in HMEC’s) and knowledge regarding the role of TFAP2C in melanomas is rather limited, we focused additional investigations on this association." (PMID 24023917, 2013). "Downregulation of ECM1 did not appear to affect cell migration or invasion in either of the melanoma cell lines (data not shown)." (PMID 24023917, 2013). "While we did not note alterations in these characteristics in the melanoma lines examined, ECM1 downregulation does appear to significantly affect cell attachment." (PMID 24023917, 2013). "Since TFAP2A and C have been reported as possible upstream regulators of ECM1 expression in prior studies from our lab and TFAP2 is an important regulator of melanoma pathogenesis, we also examined expression of these AP2 factors in the melanoma cell lines that were evaluated for ECM1 expression." (PMID 24023917, 2013). "The status of ECM1 expression is melanomas has not been previously examined." (PMID 24023917, 2013).
pancreatic cancer (2 papers, 2022 to 2025). "In pancreatic cancer cells, miR-193a-5p is upregulated and involved in the activation of serine/arginine-rich splicing factor 6 (SRSF6), OGDHL, extracellular matrix protein 1 (ECM1), and epithelial-mesenchymal transition (EMT)." (PMID 40161373, 2025).
pancreatic ductal adenocarcinoma (2 papers, 2020 to 2024). An infiltrating adenocarcinoma that arises from the epithelial cells of the pancreas. "Additionally, miR-23a-5p has been identified to suppress the growth and invasion of pancreatic ductal adenocarcinoma cells through the inhibition of ECM1 expression." (PMID 38720802, 2024). "Besides, studies based on pancreatic ductal adenocarcinoma suggested that increased ECM1 expression abrogated the anti-tumor effect exerted by miR-23a-5p." (PMID 32292720, 2020).
psoriasis (2 papers, 2020 to 2024). An autoimmune condition characterized by red, well-delineated plaques with silvery scales that are usually on the extensor surfaces and scalp. "ECM1 has been implicated in pathological processes, such as excessive angiogenesis and vasodilation in conditions like psoriasis." (PMID 38172938, 2024). "ECM1 is also involved in the excessive angiogenesis and vasodilation observed in psoriasis." (PMID 32602849, 2020).
adenoma (1 paper, 2016). A neoplasm arising from the epithelium. "The genes CDH3, ECM1, IGFBP2, and MET, which are associated with cell adhesion, the extracellular matrix, and cancer cell invasion/metastasis, are also observed frequently increased in these two adenoma samples." (PMID 27100181, 2016).
airway allergies (1 paper, 2022). "This scenario was also compounded through the finding that chimeric BALB/c mice transplanted with ECM1-deficient bone marrow cells showed a decrease in inflammatory response in experimentally induced airway allergy." (PMID 36553077, 2022).
Arthritis (1 paper, 2020). Inflammation of a joint. "In the present study, several proteins, including ECM1, TGF-β2, PDGFRA, and SAA, that regulate the proliferation of human arthritis were upregulated at both the mRNA and protein levels." (PMID 32318048, 2020).
benign thyroid neoplasms (1 paper, 2015). "Upregulation of ECM1 has been revealed in malignant compared to benign thyroid neoplasms and it has been proven to be useful as a diagnostic marker for thyroid malignancy in fine needle aspiration biopsies." (PMID 25923053, 2015).
cholesteatoma (1 paper, 2014). A pathologic process characterized by the proliferation of keratinizing squamous epithelium resulting in the accumulation of keratin and cells in the middle ear and/or mastoid. "Neutrophil elastase (ELANE) and extracellular matrix protein 1 (ECM1) proteins were up-regulated in cholesteatoma." (PMID 25093596, 2014).
colon cancer (1 paper, 2018). "Of these, six mRNA including ECM1, GZMB, KLK10, CCL20, MMP9, and IL7 have been previously reported to have a prognostic role in colon cancer." (PMID 29377588, 2018).
cystinosis (1 paper, 2021). Cystinosis is a metabolic disease characterized by an accumulation of cystine inside the lysosomes, causing damage in different organs and tissues, particularly in the kidneys and eyes. "The combination of reduced ECM-1 and NAG in all studied patients further confirmed the hypothesis of OA as the cause of fertility problems in male infantile cystinosis patients." (PMID 34944047, 2021). "It was found that all infantile cystinosis patients had reduced levels of ECM-1 when compared to healthy controls without vasectomy." (PMID 34944047, 2021).
dementia (1 paper, 2024). Loss of intellectual abilities interfering with an individual's social and occupational functions. "Dementia-related proteins fibronectin (FN), FN1.3, FN1.4, Von Willebrand factor (VWF) and extracellular matrix protein 1 (ECM1) were also measured." (PMID 38397086, 2024).
depression (1 paper, 2025). "Given the findings regarding interactions with BAFF, ECM1, and TGF-β, it would be relevant to discuss the role of neuroinflammation in depression." (PMID 40004491, 2025).
edema (1 paper, 2023). An abnormal accumulation of fluid beneath the skin, or in one or more cavities of the body. "In these lung protective studies, shionone suppressed the inflammatory response, marker genes, and pathways, such as pulmonary edema, TNF-α, IL-6, and IL-1β and ECM1/STAT5/NF-κB, which again support the anti-inflammatory properties of shionone." (PMID 38202771, 2023).
encephalomyelitis (1 paper, 2022). Inflammation of the brain and the spinal cord. "Inversely, in vivo overexpression of ECM1 successfully inhibited encephalomyelitis with Th17 cell activation." (PMID 36553077, 2022). "Administration of recombinant ECM1 ameliorated the severity of encephalomyelitis with cerebral demyelination and inflammation, accompanied by a decrease in the Th17 response, in an experimental model for multiple sclerosis." (PMID 36553077, 2022).
Fibroadenoma (1 paper, 2020). A benign tumor of the breast characterized by the presence of stromal and epithelial elements. "For fibroadenoma tissues, compared with both fibroadenoma-adjacent and normal tissues, there were six up-regulated (ANXA6, VCP, SERPINH1, galactosidase alpha, NNT, and MMP11) and 38 down-regulated (KRT10, KRT1, ALDH1A1, ECM1, and others) proteins in fibroadenoma." (PMID 33194682, 2020).
Hydrocephalus (1 paper, 2020). Hydrocephalus is an active distension of the ventricular system of the brain resulting from inadequate passage of CSF from its point of production within the cerebral ventricles to its point of absorption into the systemic circulation. "Beyond verifying the occurrence of hydrocephalus, such measurements would highlight case-specific attributes, such as the presence of demyelination, revealed by the overabundance of ECM1, or of an aggressive immune response indicated by the overabundances of vitronectin and complement factors." (PMID 33192320, 2020).
Hypertension (1 paper, 2025). The presence of chronic increased pressure in the systemic arterial system. "We found extracellular matrix protein 1 (ECM-1) levels were significantly reduced in both 5-mo ZSF1 lean controls and obese rats, indicating that it may serve as a biomarker for hypertension." (PMID 41020515, 2025). "Moreover, given the significant downregulation of ECM-1 in all ZSF1 groups and time-points studied in this inflammation assay, it is possible that targeting this gene may be helpful to overcome both hypertension and HFpEF (early and late) or hypertension alone (reported in both genotypes)." (PMID 41020515, 2025).
injury (1 paper, 2021). Damage inflicted on the body as the direct or indirect result of an external force, with or without disruption of structural continuity. "In terms of interaction with serious complications in COVID‐19 patients, 6 markers (MFAP4, ECM1, CDKN2B.AS1, CAPN2, FGG, and CD147) and 2 exRNAs (SNORD33 and miR‐122‐5p) are involved in thrombosis or liver injury." (PMID 34122778, 2021).
invasive breast carcinoma (1 paper, 2023). A carcinoma that infiltrates the breast parenchyma. "Extracellular matrix protein 1 (ECM1) is significantly elevated in a number of epithelial tumors and invasive breast cancer, giving rise to metastases." (PMID 36902201, 2023).
ischemia (1 paper, 2011). A hypoperfusion of the BLOOD through an organ or tissue caused by a PATHOLOGIC CONSTRICTION or obstruction of its BLOOD VESSELS, or an absence of BLOOD CIRCULATION. "ECM1 mutations, therefore, might affect brain function, compromise homeostasis, or impair repair mechanisms independent of ischemia." (PMID 21349189, 2011).
leukemia (1 paper, 2021). A malignant (clonal) hematologic disorder, involving hematopoietic stem cells and characterized by the presence of primitive or atypical myeloid or lymphoid cells in the bone marrow and the blood. "In addition, we confirmed that the expression of the FAL1, ECM1, and FAL1 target genes was also decreased by CRISPRi JUND in leukemia cells." (PMID 34203279, 2021).
Meniere disease (1 paper, 2023). A disease of the inner ear (labyrinth) that is characterized by fluctuating sensorineural hearing loss; tinnitus; episodic vertigo; and aural fullness. "Three genes, ECM1, OTOP1, and OTOP2, harbored rare variants in Spanish patients with Meniere’s disease." (PMID 37107589, 2023). "Rare variants within ECM1, OTOP1, and OTOP2 were each identified in three adult patients with Meniere’s disease." (PMID 37107589, 2023).
mental retardation (1 paper, 2011). "The etiology of mental retardation in LP remains uncertain because currently there is no information about ECM1 expression in human brain outside of blood vessels." (PMID 21349189, 2011).
non-small cell lung carcinoma (1 paper, 2025). A group of at least three distinct histological types of lung cancer, including non-small cell squamous cell carcinoma, adenocarcinoma, and large cell carcinoma. "In 2019, a significant increase of AHSG (Alpha-2-HS-glycoprotein) and ECM1 (extracellular matrix protein 1) in NSCLC (Non-small-cell lung cancer) patients compared to healthy controls was reported." (PMID 40561796, 2025).
Obesity (1 paper, 2024). Accumulation of substantial excess body fat. "Taken together, the findings highlight the importance of sEVs in promoting BC growth and metastasis under obesity, and the impact of obesity-induced changes in the ECM1 protein level in the sEVs." (PMID 38402239, 2024). "Collectively, our data strongly suggest that obesity leads to increased ECM1 protein level in the circulating sEVs." (PMID 38402239, 2024). "In our study, we have provided evidence for the significant roles of sEVs and specifically identified ECM1 as a protein in the sEVs that promotes both metastasis and growth of BC under obesity conditions." (PMID 38402239, 2024). "Our data not only demonstrate the association between enhanced sEV ECM1 protein levels and integrin-β2 expression, but also suggest that monocytes/macrophages and adipocytes may serve as potential donor cells releasing sEVs with elevated ECM1 protein levels under obesity conditions." (PMID 38402239, 2024). "Our data shows that in obesity, extracellular matrix protein 1 (ECM1) protein levels are significantly increased in circulating sEVs, which is dependent on integrin-β2." (PMID 38402239, 2024). "If the enhanced loading of ECM1 protein into sEVs is facilitated by integrin-β2, integrin-β2 expression should be elevated in the cells under obesity conditions." (PMID 38402239, 2024). "In the mouse samples, it is particularly noteworthy that the sEVs derived KNG1 protein level in sEVs exhibited a significant upregulation of 5.65-fold, followed by a 2.63-fold upregulation in the ECM1 protein level under obesity conditions." (PMID 38402239, 2024). "It is suggested that under obesity conditions, elevated integrin-β2 in monocytes and adipocytes enhances ECM1 protein loading into the sEVs." (PMID 38402239, 2024). "In summary, our study is to highlight the significant role of ECM1 protein present in circulating sEVs, which contributes to the increased growth and metastasis of BC under obesity conditions." (PMID 38402239, 2024). "In contrast, in the E0771-bearing C57BL/6 mouse model, obesity not only led to an increase in ECM1 protein levels within sEVs, but it also resulted in a significant elevation of tumor ECM1 protein levels, as well as the downstream proteins MMP3 and S100A/B, compared to CD mice." (PMID 38402239, 2024). "Interestingly, sEVs purified from high-fat diet-induced obesity mice (D-sEVs) deliver more ECM1 protein to BC cells compared to sEVs from control diet-fed mice." (PMID 38402239, 2024). "In addition to revealing the role of ECM1 protein in enhancing BC growth and metastasis under obesity, it would be intriguing to investigate other cargo contents within the sEVs that may also contribute to BC development." (PMID 38402239, 2024). "Indeed, under obesity conditions, integrin-β2 protein level in monocytes was significantly increased; while the protein level of ECM1 was not significantly changed." (PMID 38402239, 2024). "Furthermore, our data indicates that the ECM1 protein levels in sEVs are elevated in both mouse models and non-BC individuals with obesity or overweight, suggesting that these sEVs can originate from cell types other than BC." (PMID 38402239, 2024). "Notably, CPN2 (carboxypeptidase N Subunit 2), F5 (coagulation factor V), ECM1 (extracellular matrix protein 1), KNG1 (kininogen 1), FN1 (fibronectin 1), and GPLD1 (glycosylphosphatidylinositol-specific phospholipase D1) were found to be elevated in both human and mouse sEVs under obesity conditions." (PMID 38402239, 2024). "The MRM data validated a significant elevation of ECM1, but not KNG1, in the sEVs of human subjects with obesity or overweight." (PMID 38402239, 2024).
osteoporosis (1 paper, 2025). A condition of reduced bone mass, with decreased cortical thickness and a decrease in the number and size of the trabeculae of cancellous bone (but normal chemical composition), resulting in increased fracture incidence. "Further pQTL-based MR analysis also identified ECM1 and ENPP2 as risk-promoting factors, highlighting the contribution of extracellular matrix organization and lipid metabolism to osteoporosis pathophysiology." (PMID 41029778, 2025).
pneumonia (1 paper, 2020). An acute, acute and chronic, or chronic inflammation focally or diffusely affecting the lung parenchyma, caused by an infection in one or both of the lungs (by bacteria, viruses, fungi, or mycoplasma.). "In the present study, we found that the SPA+ABCG1+ subset was enriched in the S/TB region with elevated expression of the ECM1-α6β4-ABCG1 axis in lung tissues from patients with pneumonia." (PMID 32157214, 2020). "Finally, we found that SPA+ABCG1+ cells and molecules in the ECM1-α6β4-ABCG1 axis were enriched in the S/TB region of lung tissue samples from patients with pneumonia." (PMID 32157214, 2020).
prostate tumors (1 paper, 2018). "Increased ECM1 and DKK3 mRNA expression in prostate tumors was associated with increased relapse-free survival." (PMID 29858602, 2018).
pterygium (1 paper, 2020). A wedge-shaped fibrovascular lesion arising from the bulbar conjunctiva and extending to the cornea. "This is consistent with a previous study showing that ECM1, which encodes extracellular matrix protein 1, was found significantly increased in pterygium." (PMID 32411530, 2020). "The expression of the five hub genes (ECM1, IQGAP2, FN1, GADD34, CXCL12) was determined by real-time PCR in comparisons between 10 normal conjunctival tissues and 10 pterygium tissues." (PMID 32411530, 2020).
pulmonary disease (1 paper, 2021). "Therefore, it was hypothesized that ECM1 was closely related to pulmonary disease." (PMID 35153740, 2021).
retinoblastoma (1 paper, 2023). A malignant tumor that originates in the nuclear layer of the retina. "Meanwhile, hsa-miR-486-3p inhibits retinoblastoma cell growth by regulating the target gene ECM1, and hsa-miR-7641 regulates the apoptotic marker caspase-9 and anti-apoptotic marker BCL2, establishing them as oncogenic miRNAs." (PMID 37233676, 2023).
squamous cell carcinoma (1 paper, 2019). A carcinoma arising from squamous epithelial cells. "In the same way, an increase of the expression of proteins, such as ECM1, CD9, and CD44 has been reported in EVs derived from squamous cell carcinoma cells upon mesenchymal transformation." (PMID 31453379, 2019).
vulvar lichen sclerosus (1 paper, 2025). A chronic inflammatory disorder of unknown etiology that affects the vulva. "Vulvar lichen sclerosus (VLS) involves chronic inflammation, immune dysregulation, and abnormal extracellular matrix remodeling, involving extracellular matrix protein 1 (ECM1) and non-coding RNAs, particularly miR-155." (PMID 41009377, 2025).